ERCC6L (ERCC excision repair 6 like, spindle assembly checkpoint helicase)
Description:
DNA helicase that acts as a tension sensor that associates with catenated DNA which is stretched under tension until it is resolved during anaphase. Functions as ATP-dependent DNA translocase. Can promote Holliday junction branch migration (in vitro).
Synonyms: PICH; FLJ20105; RAD26L
Tractability: PROTAC: ubiquitination databases record sites on it.
Target class: Enzyme; Hydrolase
Gene: Protein-coding gene on chromosome X (72,204,657 to 72,239,027, reverse strand). Ensembl gene ENSG00000186871.
Subcellular location: Chromosome, centromere; Chromosome, centromere, kinetochore; Chromosome
Subcellular location (Human Protein Atlas): Centrosome; Cytosol; Nucleoplasm
Pathways (Reactome):
Cell Cycle: Amplification of signal from unattached kinetochores via a MAD2 inhibitory signal; EML4 and NUDC in mitotic spindle formation; Mitotic Prometaphase; Resolution of Sister Chromatid Cohesion; Separation of Sister Chromatids
Signal Transduction: RHO GTPases Activate Formins
Gene Ontology:
Molecular function: ATP hydrolysis activity; DNA translocase activity; protein binding; ATP binding; DNA helicase activity
Cellular component: chromosome; membrane; cytosol; chromosome, centromeric region
Homologues: Orthologues: chimpanzee ERCC6L (99% identical), macaque ERCC6L (98% identical), pig ERCC6L (83% identical), dog ERCC6L (81% identical), guinea pig ERCC6L (77% identical), mouse Ercc6l (73% identical), rat Ercc6l (73% identical), rabbit ERCC6L (72% identical), tropical clawed frog ercc6l (48% identical), zebrafish ercc6l (46% identical). Paralogues in human: CHD6 (20% identical), CHD5 (19% identical), CHD7 (19% identical), CHD4 (19% identical), CHD9 (19% identical), ERCC6 (18% identical), CHD3 (18% identical), SRCAP (18% identical), CHD8 (18% identical), SMARCA4 (18% identical), CHD2 (17% identical), SMARCA2 (17% identical), and 18 more.
Diseases named in the same sentence as ERCC6L in open-access papers:
ERCC6L is named in the same sentence as 42 diseases in open-access papers, as found by Europe PMC text mining. Sharing a sentence is not in itself a finding about the gene and the disease. The quoted sentences say what the papers report.
breast carcinoma (9 papers, 2017 to 2024). "We observed that the ERCC6L mRNA increased along with the progress of breast cancer and associated with poor overall survival, at least in breast and kidney cancers, suggesting it to be an effective marker for cancer progression." (PMID 28178669, 2017). "Regarding potential clinical significance of our findings, recent work has shown that ERCC6L is often over-expressed in breast cancers and that knockdown of ERCC6L inhibits proliferation in breast cancer cells." (PMID 39561207, 2024). "Here, we found that ERCC6L was highly expressed in breast cancer, especially in TNBC, which was closely related to poor outcomes of patients." (PMID 37667329, 2023). "The mRNA levels of ERCC6L in patients with basal-like breast cancer or triple-negative breast cancer were higher than those in patients with other subtypes of breast cancer." (PMID 37667329, 2023). "In in vitro cell culture, ERCC6L acted as a tumor promoter in the malignant progression of breast cancer cells." (PMID 37667329, 2023). "Altogether, ERCC6L is essential for tumor progression and can promote the development of breast cancer." (PMID 37667329, 2023). "Recently several reports revealed that abnormal ERCC6L expression has been detected in several malignant solid tumors consisting of breast cancer, kidney cancer, and neuroblastoma." (PMID 32891122, 2020). "Higher expression of CDC25C, ERCC6L or RAD51 was related to shorter overall survival in breast cancer or specified ER-positive breast cancer (all P < 0.05)." (PMID 31506496, 2019). "To verify the role of ERCC6L in in-vitro experiment, we chose the invasive breast cancer cell line (MDA-MB-231) to perform xenograft tumor experiment in nude mice." (PMID 28178669, 2017). "Both kidney and breast cancer patients with a higher expression level of ERCC6L showed worse outcomes." (PMID 28178669, 2017). "To verify the effect of ERCC6L on cell proliferation, we knocked down ERCC6L by shRNA in another two cancer cell lines, a breast cancer cell line MDA-MB-231 and a kidney cancer cell line 786-0." (PMID 28178669, 2017). "A few studies have indicated that the knockdown of ERCC6L could induce cell cycle arrest, chromosome instability, and cell death in breast cancer cell lines." (PMID 37667329, 2023). "ERCC6L silencing decreased the phosphorylation level of MAPK in breast cancer cells." (PMID 28178669, 2017). "However, the effect of ERCC6L on the tumorigenesis and progression of breast cancer is unclear." (PMID 37667329, 2023). "In addition, high ERCC6L expression level is related to poor prognosis in breast cancer patients, and may regulate cell proliferation, invasion and metastasis by regulating different single pathways." (PMID 32891122, 2020). "Moreover, high expression of ERCC6L showed gradually worse outcome in breast cancer, showing significant difference at stage IV in breast cancer and in kidney cancer, suggesting that the high expression of ERCC6L is an effective prognostic biomarker in cancers, at least in breast and kidney cancers." (PMID 28178669, 2017). "ERCC6L was obviously overexpressed in patients at stage II and III phase compared to those at stage I in breast cancer." (PMID 28178669, 2017). "Additionally, we demonstrated that there is an interaction between ERCC6L and KIF4A, both of which are closely related factors in mitosis and are involved in the malignant progression of breast cancer." (PMID 37667329, 2023).
breast carcinoma (continued). "Moreover, ERCC6L and KIF4A may synergistically promote breast cancer cell proliferation, migration and invasion." (PMID 37667329, 2023).
hepatocellular carcinoma (6 papers, 2020 to 2023). A malignant tumor that arises from hepatocytes. "For example, ERCC6L overexpression is associated with disease progression and poor survival in patients with breast, renal, and hepatocellular carcinoma." (PMID 36726012, 2023). "ERCC6L expression levels are higher in tumors (breast, colorectal, and hepatocellular cancer) than in comparable normal tissue, indicating that it can be used as a biomarker for cancer patients." (PMID 36550435, 2022). "In addition, ERCC6L silencing can lead to cycle arrest, proliferation inhibition, and reduced invasion of tumor cells in renal carcinoma, breast cancer, colorectal cancer, hepatocellular carcinoma, and non-small cell lung adenocarcinoma." (PMID 36726012, 2023). "As reported, ERCC6L upregulation was demonstrated to be correlated with tumor progression and poor prognosis in hepatocellular carcinoma (HCC)." (PMID 34425559, 2021). "Notably, ERCC6L was considered to be a poor prognosis marker that promotes cancer cell proliferation, migration and/or invasion, with aberrantly high expression in a wide variety of aggressive cancers, including hepatocellular cancer and non-small cell lung adenocarcinoma." (PMID 37968758, 2023). "However, the function and molecular mechanism of the ERCC6L in hepatocellular carcinoma (HCC) have not been investigated extensively." (PMID 32891122, 2020).
kidney cancer (4 papers, 2017 to 2021). Primary or metastatic malignant neoplasm involving the kidney. "Upregulated ERCC6L mRNA was notably correlated with the progress of tumor and associated with poorer outcomes in breast and kidney cancer patients." (PMID 32891122, 2020). "We further analyzed the association of ERCC6L expression with survival rates at different stages in breast and kidney cancers." (PMID 28178669, 2017). "In addition, higher ERCC6L expression was found to be significantly associated with worse clinical survival in breast and kidney cancers." (PMID 28178669, 2017). "Here we report for the first time that ERCC6L knockdown significantly inhibited cell proliferation in vitro and supressed tumor growth in vivo, and its high expression is significantly associated with bad outcome and progress in cancers, at least in breast and kidney cancers." (PMID 28178669, 2017). "In this study, we took breast and kidney cancers for examples and demonstrated for the first time that ERCC6L silencing inhibited the proliferation of cancer cells, and tumor growth in nude mice." (PMID 28178669, 2017).
lung carcinoma (4 papers, 2019 to 2025). "Single nucleotide polymorphisms (SNP) in genes, such as ALDH7A1, POLA2, LIG1, and ERCC6L, are important for the development of various cancers, such as esophageal squamous cell carcinoma, lung cancer, and oral cancer, but these polymorphic genes may be linked with pathogenesis of BRCA." (PMID 31311202, 2019). "Here, we demonstrate that ERCC6L plays a critical role in promoting lung cancer stemness by stabilizing HIF-1α expression." (PMID 40691138, 2025).
gastric cancer (3 papers, 2021 to 2025). A primary or metastatic malignant neoplasm involving the stomach. "Moreover, the tumor-promoting functions of ERCC6L have been confirmed in renal cell carcinoma, gastric cancer, and colorectal cancer." (PMID 36550435, 2022). "Relationship between ERCC6L expression and clinicopathological parameters in gastric cancer." (PMID 34425559, 2021). "However, the role of ERCC6L in the progression of gastric cancer (GC) remains to be elucidated." (PMID 34425559, 2021). "Kaplan-Meier survival curves indicated that patients with high expression of ERCC6L and MYB had significantly longer survival than those with low expression (P < 0.05), suggesting that high expression of these two genes may be associated with improved prognosis in gastric cancer patients." (PMID 40672391, 2025). "We conducted a qPCR experiment on 7 pairs of cancerous and adjacent tissues, finding that ERCC6L and MYB expression was significantly higher in gastric cancer tissues." (PMID 40672391, 2025).
triple-negative breast carcinoma (3 papers, 2019 to 2024). An invasive breast carcinoma which is negative for expression of estrogen receptor (ER), progesterone receptor (PR), and human epidermal growth factor receptor 2 (HER2). "Similarly, loss of ERCC6L in triple negative breast cancer causes chromosome instability and cell death." (PMID 39561207, 2024).
breast tumor (2 papers, 2019 to 2023). "There was a direct interaction between KIF4A and ERCC6L, and both are closely associated with mitosis and contribute to growth and metastasis of breast tumor." (PMID 37667329, 2023). "Therefore, we speculated that ERCC6L might be involved in the malignant progression of breast tumors." (PMID 37667329, 2023). "However, ERCC6L−/− and ERCC6L+/− mice did not develop mammary gland tumors, which suggested that ERCC6L knockout does not induce tumorigenesis alone and might not be a breast tumor susceptibility gene such as BRCA1/2." (PMID 37667329, 2023).
glioma (2 papers, 2022 to 2024). A benign or malignant brain and spinal cord tumor that arises from glial cells (astrocytes, oligodendrocytes, ependymal cells). "These genes were upregulated in HB cells, along with the DNA excision repair gene ERCC6L, a pan-cancer marker that promotes growth and invasion in various cancers, including glioma." (PMID 38251863, 2024).
lung adenocarcinoma (2 papers, 2025). A carcinoma that arises from the lung and is characterized by the presence of malignant glandular epithelial cells. "To elucidate whether HIF1α participates in regulating the malignant features of lung adenocarcinoma mediated by ERCC6L, we silenced HIF1α in ERCC6L-overexpressing A549 cells." (PMID 40691138, 2025).
neuroblastoma (2 papers, 2020 to 2025). Neuroblastoma (NB) is the most common solid, extracranial childhood tumor. "Furthermore, they identified that some special genes such as MAD2L, CCNB1 and BIRC5, which had a close relationship with ERCC6L were involved in the cell cycle pathway, thus ERCC6L may play an important role in neuroblastoma." (PMID 32891122, 2020).
acute myeloid leukemia (1 paper, 2022). Acute myeloid leukemia (AML) is a group of neoplasms arising from precursor cells committed to the myeloid cell-line differentiation. "However, decreased ERCC6L levels were observed in patients with acute myeloid leukemia (LAML)." (PMID 36550435, 2022).
gastric adenocarcinoma (1 paper, 2025). "In vitro experiments demonstrated elevated mRNA expression of ERCC6L and MYB in human gastric adenocarcinoma AGS and HGC-27 cells compared to normal gastric epithelial GES-1 cells." (PMID 40672391, 2025).
Infertility (1 paper, 2022). "This search revealed that in the case of NANOS1 overexpression, three infertility related genes (CREBBP, CCNB1, and NPAS2) and five cancer-germ cell genes (CENPL, ERCC6L, KIF18A, SIAH1, and TRIM71) were present in three clusters." (PMID 35743036, 2022).
laryngeal squamous cell carcinoma (1 paper, 2023). A squamous cell carcinoma that arises from the larynx. "The role of excision repair cross-complementation group 6-like (ERCC6L) has been reported in several cancers, but little is known about its expression and function in laryngeal squamous cell carcinoma (LSCC)." (PMID 36726012, 2023).
liver cirrhosis (1 paper, 2020). "ERCC6L expression positively correlated with gender, tumor encapsulation, and pathological stage (p = 0.012, 0.004, and 0.027, respectively), but not with age, liver cirrhosis, tumor size, tumor number." (PMID 32891122, 2020).
mammary dysplasia (1 paper, 2023). "Our results first showed that ERCC6L deletion significantly reduced the number of TEBs and ductal branches and significantly inhibited the extension of mammary branch ducts into the fat pad in both 6-week-old and 8-week-old mice, which suggested mammary dysplasia." (PMID 37667329, 2023).
metastasis (1 paper, 2020). The spread or migration of cancer cells from one part of the body (where they first appeared) to another. "However, further studies are required to clarify the role of ERCC6L in lymph node metastasis of PCa." (PMID 32130760, 2020).
cancer (25 papers, 2017 to 2025). A tumor composed of atypical neoplastic, often pleomorphic cells that invade other tissues. "In general, immune cell infiltration was negatively associated with the ERCC6L levels, with various cell types being enriched in certain cancer types." (PMID 36550435, 2022). "Next, we determined the biological processes or signaling pathways associated with the expression level of ERCC6L in cancers." (PMID 36550435, 2022). "Subsequent survival analysis demonstrated that ERCC6L served as an independent diagnostic and prognostic marker for poor outcomes in most cancer types." (PMID 36550435, 2022). "Recently, it has been revealed that ERCC6L expression levels are highly linked with various cancer types." (PMID 36550435, 2022). "We comprehensively investigated the diagnostic and prognostic roles of ERCC6L in a panel of common cancers." (PMID 36550435, 2022). "Somatic gene mutations contribute to cancer initiation in some cases; therefore, we investigated the presence of somatic ERCC6L mutations in nine cancer types." (PMID 36550435, 2022). "We also systematically studied the association between genetic variants of ERCC6L and immune infiltration in various cancers." (PMID 36550435, 2022). "We also reported significant associations of ERCC6L expression with clinical survival and progress in cancers." (PMID 28178669, 2017). "Thus, we suggest that evaluating ERCC6L levels and mutations in cancer should be investigated as a potential biomarker for response to targeting RAD52, and vice versa." (PMID 39561207, 2024). "We also verified that ERCC6L was associated with poor prognosis in cancer patients and that it may be utilized as an independent prognostic biomarker in certain cancer types." (PMID 36550435, 2022). "In addition to the entire patient cohort, ERCC6L was associated with poor outcomes in the nine types of cancer patients at certain stages." (PMID 36550435, 2022). "However, a comprehensive pan-cancer investigation is required to identify the expression pattern of ERCC6L in multiple cancer types and to determine the association between ERCC6L expression level and patient survival." (PMID 36550435, 2022). "Moreover, ERCC6L levels were negatively associated with higher survival rates in some cancer patients, such as LUSC, READ, STAD, and THYM." (PMID 36550435, 2022). "ERCC6L encodes a newly discovered DNA helicase that is highly expressed in almost all cancers." (PMID 32703154, 2020). "According to our previous studies, ERCC6L might be a cancer-promoting molecule of NB, which was evidently associated with poor prognosis." (PMID 31844563, 2019). "The ERCC6L/HIF-1α axis plays a crucial functional role in enhancing cancer stemness and LUAD progression both in vitro and in vivo." (PMID 40691138, 2025). "To investigate the influence of ERCC6L on the stemness of LUAD cancer cells, we initially assessed ERCC6L expression in CSC-like cells." (PMID 40691138, 2025). "Our study reveals that ERCC6L enhances proliferation and migration and promotes cancer stemness in LUAD cells." (PMID 40691138, 2025). "Polymorphisms in ERCC genes are considered significant risk factors in various analyses, including those related to NSCLC, and the expression of ERCC6L is increased in tumor samples of various cancer types, including lung cancers." (PMID 39582530, 2024). "More broadly, pan-cancer studies of altered ERCC6L expression have identified increased ERCC6L expression as a marker of poor prognosis in multiple types of cancer." (PMID 39561207, 2024). "ERCC6L is a recently discovered DNA helicase that is highly expressed in various cancer cells, promoting cell cycle progression and stimulating cancer cell proliferation." (PMID 38664976, 2024). "On the other hand, the role of ERCC6L has been reported in several cancers, but little is known about its expression and function in LSCC." (PMID 36726012, 2023).